EPHA7 (EPH receptor A7)
Diseases named in the same sentence as EPHA7 in open-access papers (continued):
Sharing a sentence is not in itself a finding about the gene and the disease.
cancer (37 papers, 2008 to 2025). A tumor composed of atypical neoplastic, often pleomorphic cells that invade other tissues. "EphA7 (Ephrin type-A receptor 7) is a member of this group, but there is still insufficient information in the literature about its association with cancer." (PMID 39329983, 2024). "As a member of the Eph receptor group, EphA7 is associated with carcinogenesis but plays a contradictory role in different cancers." (PMID 35681118, 2022). "Still, the predictive value of EPHA7 mutation with regard to cancer types needs to be verified in future prospective trials." (PMID 33526018, 2021). "Genes with putative miR-200a targeting sequences that have been implicated in cell migration and cancer include Abelson murine leukemia viral oncogene homolog 2 (Abl2), deleted in liver cancer 1 (Dlc1), Eph receptor A7 (EphA7), and Zeb1." (PMID 20957176, 2010). "Besides, EPHA7 mutations have been demonstrated to be predictive biomarkers for immune checkpoint blockades in several cancer types." (PMID 36305643, 2022). "Three additional predicted cancer driver mutations (EPHA7, MAP3K12, and PCSK5) were identified that were acquired during the transformation of non‐malignant MCF10A cells to malignant DCIS.com cells that could also be implicated in the cell‐context dependency of SOX11 in promoting invasion." (PMID 28707729, 2017). "MEGM DEGs are mainly associated with the topics ‘cancer’, ‘neuro’ and ‘eye & retina’ or two combined topics like ‘cancer and neuro’ (SEMA3C, ROR1, EPHA7, GDNFR) or ‘eye & retina and neuro’ (PRDM8, CRYBG3)." (PMID 39695086, 2024). "CCR5, CCL5, PDGF-BB, and EphA7 levels, which have been identified in the carcinogenesis of many cancers, were measured in the blood samples using the ELISA method." (PMID 39329983, 2024). "It was revealed that several top up‐regulated genes such as KANK1, GALNT14, TMEM98, and PTPN3 and top down‐regulated genes such as PITX2, SNCA, and EPHA7 play key roles in cancer progression and chemotherapy response." (PMID 37937323, 2023). "In our dataset, in addition to EPHB1, we also identified EPHA1, EPHA2 and EPHA7 that were highly phosphorylated in cancer compared to normal tissue, making these proteins as potential therapeutic targets." (PMID 36093296, 2022). "According to the UALCAN website, the EphA7 promoter was hypermethylated in 15 of 23 categories of cancer (P < 0.05) compared with adjacent normal tissues." (PMID 35681118, 2022). "Our study additionally identified a similar role for EPHA7 and ZFHX3 mutations in NSCLC, consistent with prior observations from a large pan-cancer cohort." (PMID 35798829, 2022). "The role of EphA7 in cancer is very controversial and context-dependent, with reports suggesting both pro-malignant and anti-tumorigenic function." (PMID 36471440, 2022). "For example, EphA2 is highly expressed in certain human cancers and plays a role as an oncogene, while EphA7, an Eph receptor, plays roles in the development of the central and peripheral nervous system, limb patterning, and innervation." (PMID 35103233, 2022). "Some kinases identified had lower kinase activity in cancer compared to normal tissue, amongst them Lmr1, EPHA7 and JAK1." (PMID 36093296, 2022). "We then further analyzed cancer subgroups in TCGA cohort, which showed a generally and numerically worse prognosis of EPHA7-MUT patients within each cancer type." (PMID 33526018, 2021). "Eph receptor A7 (EPHA7) belongs to the receptor subfamily of theprotein-tyrosine kinase family, which inhibits cancer survival and migration via a ligand andtyrosine kinase dependent signaling (Oricchio etal., 2011)." (PMID 33196759, 2020). "Of the other 16 genes, COL5A1, GABBR1, HACE1, EPHA7, and TRIP11 have well-documented associations with cancer." (PMID 30962767, 2019). "EphA7 is part of this family, but there have been only a limited number of studies that investigate its connection with cancer." (PMID 31505877, 2019).
cancer (continued). "With PDGF-BB levels above 350 ng/L or EphA7 levels above 200 ng/mL, the cancer probability reached 100%." (PMID 31505877, 2019). "In summary, elevated expression of EPHA7 is a poor prognostic factor for many cancers and is correlated with cancer progression and metastasis." (PMID 28611294, 2017). "EphA7 is located on 6q16.1, a region in close proximity to the chromosome 6 breakpoint found in various types of cancer." (PMID 18366728, 2008). "EPHA7 has been found dysregulated in many cancers and may display both a pro-oncogenic and an anti-oncogenic activity." (PMID 41516312, 2025). "Although expression of EPHA7 and myoferlin was not correlated, EPHA7 expression was independently associated with progression-free (HR = 1.237–4.319) and cancer-specific survival (HR = 1.214–4.558)." (PMID 35205843, 2022). "Expression of EphA7 has been detected in some types of human cancer." (PMID 35103233, 2022). "EPHA7-MUT successfully predicted better clinical outcomes in ICI-treated patients across multiple cancer types, indicating that EPHA7-MUT could serve as a potential predictive biomarker for immune checkpoint inhibitors." (PMID 33526018, 2021). "Survival analysis in both non-ICI-treated cohort and TCGA cohort revealed longer median OS in EPHAT-WT instead of EPHA7-MUT patients, indicating that EPHA7-MUT might potentially have a worse prognostic impact on cancer patients." (PMID 33526018, 2021). "Interestingly, the expression of EPHA7 in these cancers was intensified, and our results were similar to these studies." (PMID 33439936, 2021). "Therefore, EPHA7-MUT has the potential to serve as a predictive biomarker for immune checkpoint blockades across multiple cancer types." (PMID 33526018, 2021). "The molecular mechanism of EPHA7 in different cancers is variable, and EPHA7 may exert tissue-specific or cell-specific functions." (PMID 33439936, 2021). "Specifically, altered EPHA7 expression in humans has been implicated in several cancers and neurological deficits, with no distinction as to which isoforms are involved." (PMID 33275600, 2020). "Using a set of mutations from 22 cancers we detect 151 putative cancer drivers, of which 79 are not listed in cancer resources and include recently validated cancer associated genes EPHA7, DCC netrin-1 receptor and zinc-finger protein ZNF479." (PMID 30670742, 2019). "However, despite these observations, only EPHA7 mutations had a statistically significant relationship with overall survival in NSCLC patients, failing to achieve statistical significance in any other cancer type." (PMID 35798829, 2022). "Thus, high levels of EPHA7 may have the effect of sequestering microRNAs and reducing proliferation in other cancers." (PMID 30962767, 2019). "We provide evidence that EphA7 is overexpressed in GBM and suggest that this receptor might be used as a new diagnostic and prognostic marker for further Eph/ephrin targeted molecular cancer therapy." (PMID 18366728, 2008). "In particular, NOTCH2 H107P and BCR T1127S variants were almost clonal (i.e., present in all somatic cells), whereas EPHA7 L564F and MTOR S920F were subclonal alterations, present in around 35% of cancer cells." (PMID 39421445, 2024). "Our study demonstrated the robust link between EPHA7-MUT and better clinical outcomes in ICI-treated cancer patients." (PMID 33526018, 2021). "We also gave consideration to EPHA7, another member of the ephrin type A receptor family: despite not corresponding FDR-adjusted p-value cut-off (FDR = 0.0599 > 0.05), its expression showed a 3-fold decrease in early invasive cancer compared to CIN3/cancer in situ." (PMID 32899940, 2020).
infection (4 papers, 2016 to 2021). The state of being infected such as from the introduction of a foreign agent such as serum, vaccine, antigenic substance or organism. "In contrast, we observed an ~2-fold higher infection of RRV-YFP gHΔ21–27 on EphA7 overexpression cells, when compared to RRV-YFP wt." (PMID 33657166, 2021). "RRV-YFP wt infection increased from 0.14 ± 0.04% on empty vector transduced Raji cells to ~8.5% upon EphA7 overexpression and to ~17% upon Plxdc1/2 overexpression, without pronounced differences between the Plxdc family members." (PMID 33657166, 2021). "The volume of parvalbumin-positive structures attributed to basket cell terminals was localised on EGFP-positive granule cell somata and taken as a measure for basket cell innervation after infection with an EphA7 knockdown vector." (PMID 27405707, 2016). "As EphA4, EphA5, and EphA7, which are low-affinity receptors for KSHV, are expressed in B cells, these receptors play a crucial role in the infection of B cells by KSHV16,18,19,30." (PMID 33235207, 2020). "EphA7, which had previously been described by our group to be critical for RRV infection of BJAB B lymphocytes enhanced RRV-YFP wt infection to 44.4% while infection with the Eph-binding-negative mutant RRV-YFP gH-AELAAN was not affected." (PMID 33657166, 2021).
EPHA7 also shares sentences with these, for which no sentence is quoted: acute lymphoblastic leukemia (2 papers); metastatic disease (2); adenocarcinoma (1); asthma (1); basal cell carcinoma (1); bladder cancer (1); bone sarcoma (1); brain tumor (1); cervical adenocarcinoma (1); cervical disease (1); cutaneous melanoma (1); Depression (1); endocervical adenocarcinoma (1); endometrial carcinoma (1); hyperlipidemia (1); hypotrichosis (1); inflammatory myofibroblastic tumor (1); Insulin resistance (1); invasive breast carcinoma (1); invasive ductal carcinoma (1); kidney tumors (1); myopia (1); neuroblastoma (1); neurodevelopmental disorder (1); neuroendocrine tumors (1); Obesity (1); panic disorder (1); paraganglioma (1); phaeochromocytomas (1); prostate (1).
A further 6 diseases each share a sentence with EPHA7 in 1 paper.